RNU6-16P (RNA, U6 small nuclear 16, pseudogene)
Synonyms: RNU6-16
Gene: Small nuclear RNA gene on chromosome 11 (88,612,805 to 88,612,911, reverse strand). Ensembl gene ENSG00000207113.
Homologues: Orthologues: pig U6 (99% identical), chimpanzee U6 (98% identical), macaque U6 (98% identical), tropical clawed frog U6 (98% identical). Paralogues in human: RNU6-1 (97% identical), RNU6-2 (97% identical), RNU6-39P (97% identical), RNU6-3P (97% identical), RNU6-4P (97% identical), RNU6-5P (97% identical), RNU6-6P (97% identical), RNU6-9 (97% identical), RNU6-12P (96% identical), RNU6-13P (96% identical), RNU6-17P (96% identical), RNU6-18P (96% identical), and 1283 more.